AFP (alpha fetoprotein)
Diseases named in the same sentence as AFP in open-access papers (continued):
Sharing a sentence is not in itself a finding about the gene and the disease.
liver cancer (continued). "The combined detection of contrast-enhanced ultrasound and enhanced CT, AFP, and CA199 significantly improved the sensitivity and accuracy of liver cancer diagnosis." (PMID 35237392, 2022). "Serum alpha-fetoprotein (AFP) detection, B ultrasound, and CT scans can be used to diagnose liver cancer." (PMID 35659256, 2022). "Progression-free survival (PFS) was consistent through treatment lines, modified albumin–bilirubin (mALBI) grade, Barcelona Clinic for Liver Cancer (BCLC) stage, and α-fetoprotein (AFP) level." (PMID 35740647, 2022). "We examined blood samples from HBL patients with active β-catenin-TCF4 pathways in primary liver cancer and discovered GPC3 and AFP in their bloodstream." (PMID 36551548, 2022). "Our study found that serum anti-14-3-3 zeta autoantibody is a potential non-invasive serum biomarker for predicting hepatocarcinogenesis, which might significantly improve the diagnosis efficiency for early and AFP-negative liver cancer and reduce the associated fatality rate to a certain extent." (PMID 34722278, 2021). "Meanwhile, AFP is less sensitive to intrahepatic cholangiocarcinoma (ICC), which further highlights its incapability in diagnosing different types of liver cancer." (PMID 34348726, 2021). "Efforts have been made to select appropriate candidates for TACE and RFA treatment based on the Barcelona Clinic Liver Cancer (BCLC) staging system and on histopathologic grade, AFP and performance status as well as vascular invasion." (PMID 34532340, 2021). "Exosomes derived from liver cancer cells containing alpha fetoprotein (AFP) mRNA and glypican‐3 mRNA are used for the diagnosis and treatment of liver cancer." (PMID 33247543, 2021). "AFP, alpha‐fetoprotein; BCLC, Barcelona Clinic Liver Cancer; B, hepatitis B surface (HBs) antigen‐positive; C, hepatitis C virus (HCV) antibody‐positive; NBNC, HBs antigen‐negative and HCV antibody‐negative; NA, not assessed." (PMID 33834612, 2021). "We decided to continue the study with the HepG2 line because they expressed liver-specific and hepatic cancer stem cells markers such as CD133, alpha fetoprotein, GAPDH, and albumin." (PMID 34577545, 2021). "The serum tumor markers, AFP,41–44 CA125, and CA19-9,45–48 were chosen because these proteins have been identified in various human cancers, including liver cancer." (PMID 34857736, 2021). "This study aimed to explore the clinical value of AFP and ICAM-1 to judge surgical prognosis and evaluate potential therapeutic effects for patients with liver cancer." (PMID 34696675, 2021). "At present, Alpha-fetoprotein (AFP), as a common marker, is widely used in the diagnosis of liver cancer patients." (PMID 33672380, 2021). "When comparing by PC size, groups were balanced by age, gender, performance status, Barcelona Clinic Liver Cancer (BCLC) staging, and AFP level (≥400 μg/L vs. < 400 μg/L)." (PMID 33445517, 2021). "The diagnostic value of GAPR combined with GAR and AAR was higher in AFP‐NHCC and was also reflected in the TNM stage, Barcelona Clinic Liver Cancer (BCLC) stage and tumor size." (PMID 34145988, 2021). "Traditional markers, such as CA125, CA199 and alpha-fetoprotein (AFP), are frequently used to diagnose OC, gastric cancer and liver cancer, predicting prognosis, and monitoring postoperative recurrence, respectively." (PMID 34041016, 2021). "AFP-induced overexpression of Fas on the surface of lymphocytes, together with simultaneous over-secreted Fas-L from tumor cells, such as Bel 7402 cells, could be one of the reasons to accelerate the death of lymphocytes and facilitate the immune escape of liver cancers." (PMID 34680245, 2021). "AFP has been used as a tumor marker of HCC and plays an essential role in liver cancer screening, diagnosis, monitoring, and prognosis prediction, but its biological functions are still poorly understood." (PMID 32774373, 2020).
liver cancer (continued). "Patients with liver cancer were more likely to be male, positive for HBsAg and antibody to hepatitis C virus, having higher ALT, total bilirubin, and alpha‐fetoprotein, as compared to patients who had non‐liver malignancies." (PMID 32780516, 2020). "Thus, demethylation AFP promoter may be a reason for aberrant AFP expression in some liver cancers." (PMID 31897235, 2020). "The levels of FPR and GPR were gradually increased in the development of AFP-NHCC and positively correlated with the tumor size and Barcelona Clinic Liver Cancer (BCLC) stages." (PMID 32190001, 2020). "It is also worth noting that 15.4–30.6% of patients with liver cancer cannot be well diagnosed even when CD166, MCAM, CCT3 and AFP were combined used, this led us to discover more useful biomarkers to overcome this problem." (PMID 31501420, 2019). "We found that the true positive rate of liver cancer can be increased by the combined usage of previously discovered CD166 and MCAM, current identified CCT3 and traditional AFP." (PMID 31501420, 2019). "The results of liver general appearance, histopathological examination and the levels of AFP and ALT, indicated that OB had good anti-liver cancer activity in vivo, it is also shown that the study of OB as an anticancer drug is valuable and necessary." (PMID 31801250, 2019). "For example, the synergistic effect of electron donor generation and photoactive species introduction was used to detect alpha-fetoprotein (AFP), which is a biomarker for liver cancer." (PMID 31572709, 2019). "For liver cancer in particular, CV890, which was regulated by an AFP-promoter, selectively replicates in AFP-producing cells." (PMID 31781493, 2019). "Thus, our results suggest that celastrol could reduce the serum level of the liver cancer marker AFP, which is attributable to the down-regulating effects of celastrol on the AFP mRNA transcriptional levels in mouse livers exhibiting AKT/c-Met hepatocarcinogenesis." (PMID 35539339, 2018). "The study also aimed to reveal the correlation between lamin B1 mRNA levels with the tumor size and the number of tumor nodules, represented using the Barcelona-Clinic Liver Cancer (BCLC) Staging System12, as well as to serum AFP level." (PMID 30467522, 2018). "The JIS system was created in 2003 by the Liver Cancer Study Group of Japan (LCSGJ) and was later improved upon and modified in TNM (JIS-TNM-Child) and JIS-TNM-Child plus alpha fetoprotein (JISTNMAFPChild)." (PMID 29617435, 2018). "This is also in accordance with the results of Zhanget al.21, who concluded that AFP can act as an independent prognostic factor for HCC, as it can induce the malignant progression of liver cancer via tumorigenesis and cellular growth, migration and invasion." (PMID 30467522, 2018). "Endogenous AFP mRNA and protein expression were detected in HEK293T cells and in the liver cancer cell lines HepG2, PLC/PRF5, SNU495, and CL48." (PMID 29858076, 2018). "In the univariate analysis, significant prognostic indicators of HCC overall survival included the PRMT1 signature, alpha-fetoprotein (AFP), tumor size, and Barcelona Clinic Liver Cancer (BCLC) stage." (PMID 29383172, 2017). "Our data further showed that lower expression of hsa_circ_0004018 was correlated with serum alpha-fetoprotein (AFP) level, tumor diameters, differentiation, Barcelona Clinic Liver Cancer stage and Tumor-node-metastasis stage." (PMID 28938566, 2017). "ChV was also able to reduce the expression of M2-PK, as was also seen with AFP and TGF-β in liver cancer induced rats." (PMID 29268718, 2017). "To this end, we identified two distinctive markers of HCC, CHALV1 and AFP, which are highly expressed in HCC cell lines and liver cancer patient-derived materials." (PMID 27756242, 2016). "AFP has been a useful biomarker for diagnosis of HCC since the 1970s and currently is widely used in the clinical diagnosis of liver cancer." (PMID 25749381, 2015).
liver cancer (continued). "In this study, we found out that Tregs was significantly reduced after transfusion of DC-CTL/CIK cells companied by decreasing serological tumor markers including AFP, CA199 and CA242 in primary liver cancer and CA724 in gastric cancer." (PMID 26561538, 2015). "Among the 6 common tumor markers, the serum levels of AFP, CA19-9 and CA242 post-treatment were significantly lower than that of pre-therapy in primary liver cancer (p < 0.05)." (PMID 26561538, 2015). "This immunoassay shed light on potential applications in simultaneous gastric cancer (related biomarkers: CEA, CA199, CA724) and liver cancer diagnosis (related biomarkers: CEA, CA199, AFP)." (PMID 26577799, 2015). "Regular monitoring of blood α-fetoprotein (AFP) and/or carcino-embryonic antigen (CEA) levels is important for the routine screening of liver cancer." (PMID 26610504, 2015). "There were significant differences between the two groups in term of alpha-fetoprotein (α-FP) level (p<0.01), tumor size (p<0.01), TNM stage (p<0.01), recurrence incidence (p<0.01) and family history of liver cancer (p<0.01)." (PMID 23556002, 2013). "Significant enrichment was determined for AFP (Alpha-fetoprotein) and BCLC (Barcelona clinic liver cancer) stage using Fisher's exact test right-tailed for both cases." (PMID 24223834, 2013). "Alpha-fetoprotein (AFP) is a widely used marker for surveillance and early detection of hepatic cancers." (PMID 23519104, 2013). "Prognostic factors including age, gender, Child-Pugh status, serum AFP concentration, HBV, GTV, Barcelona Clinic Liver Cancer (BCLC) stage, portal vein thrombosis, TACE times, radiation dose and HIFU times were evaluated by univariate analysis." (PMID 23554758, 2012). "Quadruple-regulated adenoviruses carrying an AFP promoter-controlled HCCS1 gene showed reduced toxicity and excellent anti-liver cancer efficacy in this study." (PMID 22040050, 2011). "Only 31% of health workers knew that alpha-fetoprotein (AFP), alanine aminotransferase (ALT), and ultrasound tests should be performed to test liver function and screen for liver cancer in someone chronically infected with HBV." (PMID 20184740, 2010). "In assessing relations to histologic type and pathologic stage in primary liver cancer, we compared serum CYFRA 21-1 with three widely used tumour markers: AFP, CEA, and CA 19-9 in large number of patients with primary liver cancer." (PMID 12799633, 2003). "Researchers utilized alpha-fetoprotein (AFP), a specific marker for liver cancer, to test the hypothesis that peptide-MHC complexes could be targets for CAR T-cell therapy against solid tumors." (PMID 40098955, 2025). "Additionally, IL-37 expression correlated with serum alpha-fetoprotein and tumor size in HCC and paracancerous tissues, showing a negative correlation with NF-κB protein expression in HCC tissues and liver cancer cell lines." (PMID 40444012, 2025). "(iv) While this study used AFP as a liver cancer marker, it did not include PIVKA‐II, a tumor marker for diagnosing HCC that is produced in cases of vitamin K deficiency or inhibition." (PMID 40589150, 2025). "In addition, staining of alpha-fetoprotein (AFP), an indicator of metastasis severity and of the immunosuppressive tumor microenvironment of liver cancer, was also reduced in the HCC tumor sections." (PMID 41286115, 2025). "Therefore, even if the prevalence of this type of liver cancer is very low, sHCC‐ICC should be suspected in patients with a simultaneous increase in serum levels of AFP and CA19‐9." (PMID 39948704, 2025). "Recent studies have also attempted to construct clinical prediction models for AFP-negative liver cancer." (PMID 40161339, 2025). "Similarly, alpha-fetoprotein (AFP), the most reliable marker for primary liver cancer diagnosis, also faces challenges in sensitivity and specificity." (PMID 40051704, 2025).
liver cancer (continued). "As previously stated, AFP has a rather low specificity since it can be raised in liver cancers that are not HCC and other chronic inflammatory diseases." (PMID 41201177, 2025). "It remained a controversial biomarker for liver cancer, as many patients exhibit negative AFP and its sensitivity and specificity are not high, similar to some previous research findings." (PMID 38448905, 2024). "In this study, based on a considerable previous effort about the relationship between Mex3a levels and liver cancer development, we propose that a more effective strategy for detecting HCC is the combined test of AFP, Mex3a mRNA levels, and Mex3a promoter methylation levels." (PMID 39564121, 2024). "Both DCP and AFP levels were elevated in the blood of mice with liver cancer, but not in HFHSD-induced diabetic mice and ND-fed healthy mice after five consecutive miR-10a/b mimic injections at 5 months." (PMID 38396943, 2024). "The traditional liver cancer monitoring indicator AFP did not have significant prognostic value in this study." (PMID 38448905, 2024). "On preoperative examination, tumor markers, including alpha-fetoprotein, carcinoembryonic antigen, and serum carbohydrate antigen, were in the normal range; therefore, disease related to liver cancer was not considered in this patient’s diagnosis." (PMID 39969350, 2024). "Staging systems such as the Barcelona Clinic Liver Cancer (BCLC) evaluate these aspects, along with objective scores like the Model for End-stage Liver Disease (MELD), the albumin–bilirubin (ALBI) score, and biomarkers such as alpha-fetoprotein (AFP)." (PMID 38396445, 2024). "Furthermore, the levels of PTX3, AFP, and CA199 were significantly elevated in the liver cancer group compared to the healthy control group (P < .05)." (PMID 39686456, 2024). "We also conducted subgroup analyses using risk ratios extracted from each study, including viral etiology, Barcelona Clinic Liver Cancer (BCLC) staging, alpha-fetoprotein (AFP) levels, macrovascular invasion or portal vein tumor thrombosis, and extrahepatic spread." (PMID 38434681, 2024). "Alpha-fetoprotein (AFP) is an important tumor marker for diagnosing and treating liver cancer." (PMID 38660138, 2024). "In clinical practice, 30%-40% of patients with malignant liver tumors still have negative AFP levels even in the advanced stage of the disease." (PMID 39759152, 2024). "In a sorafenib-treated liver cancer cohort, differences in AFP expression between responsive and non-responsive groups were observed, suggesting AFP's potential in predicting sorafenib response." (PMID 39135041, 2024). "While previous studies have explored the relationship between T2DM and liver cancer risk, our study also revealed that HCC patients with diabetes mellitus were more likely to exhibit negative AFP and abnormal prothrombin events." (PMID 39432605, 2024). "Chi-squared test analysis revealed several factors significantly associated with negative AFP and PIVKA-II in liver cancer within this population." (PMID 39432605, 2024). "Although alpha-fetoprotein (AFP) is commonly used as a serum biomarker for HCC detection and diagnosis, its effectiveness is restricted, and no other reliable biomarkers can facilitate precision medicine in primary liver cancer." (PMID 37215109, 2023). "Elevated AFP and DCP levels are typical features of liver cancer." (PMID 37035138, 2023). "When combined with AFP, the sensitivity of OPN in the diagnosis of liver cancers increases to 65%." (PMID 37575092, 2023). "Alpha-fetoprotein may also be expressed but is reported to lack sensitivity similar to EMA, B72.3, and others and has even been investigated in canine primary liver cancers." (PMID 36672443, 2023). "Fifteen patients (78.9%) were male, 9 (47.4%) had non-viral HCC, 15 (78.9%) had Barcelona Clinic Liver Cancer stage C, and median alpha fetoprotein (AFP) was 885 ng/mL (range, 2.1–625,505 ng/mL)." (PMID 37296914, 2023).
liver cancer (continued). "Some liver cancer staging systems, such as the Biomarker Combined Japan Integrated Staging (bm-JIS) and the CLIP score, also utilize serum AFP levels, whereas AFP levels ≤400 ng/mL are included in the Hangzhou criteria as a patient selection criterion before liver transplantation." (PMID 37124520, 2023). "The alpha-fetoprotein (AFP) showed no significance between before and after treatment for primary liver cancer patients (P=0.295)." (PMID 37153689, 2023). "Further analysis revealed correlations between clinical indicators and intestinal microbiome, such as a positive correlation between Veillonella and AFP in the primary liver cancer group and a negative correlation between Subdolicapsulum and AFP." (PMID 38169837, 2023). "Many patients with liver cancer have no obvious specific symptoms in early stages, and liver cancer is often discovered incidentally during liver disease follow-up or when combined with liver ultrasound and AFP testing." (PMID 38086834, 2023). "In the present study, using 20 ng/mL as a cut-off, 35.51% of HCC patients were AFP negative, which is consistent with previous reports indicating that approximately 30% of liver cancer patients were consistently negative for serum AFP." (PMID 37189543, 2023). "Given that CAP2 was already identified as a marker for early-stage liver cancer patients with negative alpha fetoprotein (AFP), we decided to focus our research analysis on the potential of ITGA6 as a diagnostic marker for early-stage liver cancer." (PMID 37627184, 2023). "Currently used biomarkers include those for the diagnosis and prognosis of tumors such as alpha-fetoprotein (AFP) for liver cancer and cytokeratin (CYFRA) 21-1 for non-small cell lung cancer." (PMID 37304241, 2023). "In addition, it has been reported that the combined detection of contrast-enhanced ultrasound and enhanced CT, AFP, and CA199 can effectively improve the sensitivity and specificity of liver cancer diagnosis, which is conducive to early screening of disease." (PMID 35237392, 2022). "Serological tests for alpha-fetoprotein (AFP), alkaline phosphatase (ALP), alanine transferase (ALT), total bilirubin (T-BIL), total protein (TP), albumin (ALB), and hepatitis B surface antigen (HBsAg) are crucial for the diagnosis of liver cancer." (PMID 36425563, 2022). "AFP and CA199 are commonly used tumor markers for the diagnosis of liver cancer." (PMID 35237392, 2022). "AFP-L3 positivity precedes identification of cancer with B-ultrasound, CT, and other imaging methods, suggesting the existence and occurrence of liver cancer; AFP-L3 is not correlated with AFP level." (PMID 35307694, 2022). "For example, AFP levels are not significantly increased in about 30–40% of confirmed liver cancer patients, while AFP is increased in some non-liver cancer patients." (PMID 35307694, 2022). "AFP and ORM1 showed strong staining in liver cancer tissues, and comparing the staining index of liver cancer tissue and normal adjacent tissue of the same patient, the expression of AFP and ORM1 in liver cancer tissue was significantly higher than that normal tissue (AFP: p = 0.035,ORM1:p < 0.001)." (PMID 36096917, 2022). "The most commonly used tumor markers for liver cancers include CA19-9, CEA, AFP, and PIVKA-II." (PMID 36556261, 2022). "The gold standard diagnostic marker for HCC is serum AFP, while the combination of AFP, CA19-9, and CEA may help with the diagnosis of primary hepatic cancer." (PMID 36559011, 2022). "Through the ROC(receiver operating characteristic) curve analysis, the recognition performance of GALAD model for liver cancer was evaluated, and the GAADPB model was established by logistic regression, including gender, age, AFP, DCP, total protein, and total bilirubin." (PMID 36620588, 2022). "AFP is the most commonly used biomarker for monitoring liver cancer, but it is still not ideal for early diagnosis of liver cancer due to its lack of sensitivity and specificity." (PMID 36157238, 2022).